NEDD4 (NEDD4 E3 ubiquitin protein ligase)
Diseases named in the same sentence as NEDD4 in open-access papers (continued):
Sharing a sentence is not in itself a finding about the gene and the disease.
hepatocellular carcinoma (19 papers, 2017 to 2025). A malignant tumor that arises from hepatocytes. "In hepatocellular carcinoma, NEDD4 has been reported to promote hepatocyte growth and migration through the PTEN/PI3K/AKT signaling pathway." (PMID 35861040, 2023). "It has been reported that NEDD4 inhibits hepatocellular carcinoma (HCC) progression; however, little is known about its potential function and molecular mechanism in HCC in the context of hepatitis B virus (HBV) infection." (PMID 33767993, 2021). "Nedd4 has been shown to participate in TGF-β signaling in hepatocellular carcinoma by regulating Smad3, though the detailed mechanism remains unclear." (PMID 41516261, 2025). "In contrast, in hepatocellular carcinoma, CFDP1 overexpression was associated with shorter OS (hazard ratio: 2, p = 0.012) and DFS (hazard ratio: 1.8, p = 0.0099), promoting cancer progression by activating the NEDD4/PTEN/PI3K/AKT signaling pathway." (PMID 38893126, 2024). "In QGY7703 and SMMC7721 hepatoma cell lines, siRNA-mediated NEDD4 knockdown assays showed that decreased expression of NEDD4 inhibited cell proliferation, invasion, and migration, promoted apoptosis, and further supported the role of the NEDD4-LATS1 pathway in HCC progression." (PMID 39544935, 2024). "The expression of NEDD4-1 has been reported to be elevated in several types of cancers including colorectal, gastric, breast, non-small-cell lung carcinoma, bladder, prostate, cervical, hepatocellular carcinoma (HCC), and glioma." (PMID 36918822, 2023). "Further, in QGY7703 and SMMC7721 hepatocellular carcinoma (HCC) cells, NEDD4 increased cell migration and invasion via inhibiting the tumor suppressor LATS1." (PMID 36293239, 2022). "To determine whether Nedd4 plays a role in other human cell lines that are susceptible to JEV infection, we assessed the effect of Nedd4 depletion on JEV infection of human neuroblastoma SH-SY5Y cells, human umbilical vein endothelial cells (HUVECs) and human hepatocellular carcinoma Huh7 cells." (PMID 28349961, 2017).
bladder cancer (17 papers, 2013 to 2025). "In mice models with NEDD4-deficient bladder cancer, an increase in PD-L1 levels within the cancer cells resulted in reduced infiltration and antitumor activity of CD8+ T cells." (PMID 38638430, 2024). "The knockdown of NEDD4 significantly suppressed the K63-linked poly-ubiquitination of KLF8 in bladder cancer cells." (PMID 37568787, 2023). "The NEDD4 gene, which is involved in protein degradation within cells, has been implicated in the growth of bladder cancer, but exactly how it promotes metastasis is unclear." (PMID 35031788, 2022). "In this study, we investigated the underlying molecular mechanism by which the NEDD4-mediated KLF8/miR-132/NRF2 axis fine-tunes the malignant phenotypes of bladder cancer cells using in vitro and in vivo assays, providing a promising therapeutic target for treating patients with bladder cancer." (PMID 35031788, 2022). "NEDD4 mediated PD-L1 ubiquitination and degradation and regulated T cell-induced immune surveillance in bladder cancer, which was regulated by fibroblast growth factor receptor 3 (FGFR3)." (PMID 38638430, 2024). "CD8+ T-cell infiltration and anticancer ability were largely impaired because of upregulation of PD-L1 in bladder tumor cells in mice with NEDD4 knockout bladder cancer." (PMID 37215134, 2023). "NEDD4 depletion using CRISPR/Cas9-sgRNA remarkably upregulated PD-L1 expression in bladder cancer cells." (PMID 37497216, 2023). "In bladder cancer, NEDD4 depletion significantly downregulated endogenous KLF8 ubiquitination, which affected the K63-linked polyubiquitination of KLF8, while K48-linked polyubiquitination remained unchanged." (PMID 37497216, 2023). "One group showed that a natural compound lycorine downregulated the expression of NEDD4 in bladder cancer, leading to suppression of cell growth and invasiveness." (PMID 37215134, 2023). "Collectively, these findings provide evidence that NEDD4 promotes bladder cancer progression by increasing the levels of KLF8 and NRF2." (PMID 37568787, 2023). "Mice with NEDD4 knockout bladder cancer display impaired CD8+ T cell infiltration and reduces anticancer activity." (PMID 36733484, 2023). "In bladder cancer, for instance, knockdown of NEDD4 inhibits cell proliferation, migration, and invasion and even induces cell apoptosis by reactivating PTEN." (PMID 36774408, 2023). "Mice with NEDD4 knockout bladder cancer displayed impaired CD8+ T cell infiltration and reduced anticancer activity because of upregulation of PD-L1." (PMID 36733484, 2023). "A critical oncogenic role of NEDD4 has been noted in bladder cancer due to its promoting function in tumor cell migration and invasion." (PMID 35031788, 2022). "The tumor tissues and adjacent normal tissues of 45 patients with bladder cancer were resected and obtained, and RT-qPCR and western blot assays were adopted to verify the expression levels of NEDD4 and KLF8." (PMID 35031788, 2022). "In bladder cancer cells, NEDD4 intensified the stability and transcriptional activity of KLF8 through ubiquitination to augment cell viability and migratory ability." (PMID 35031788, 2022). "In conclusion, this study highlights NEDD4 as a potential therapeutic target against tumor recurrence and metastasis in bladder cancer." (PMID 35031788, 2022). "They found that NEDD4 was highly expressed in bladder cancer cells, and that it stabilised and promoted the activity of a transcription factor, Kruppel-like factor 8 (KLF8)." (PMID 35031788, 2022). "In bladder cancer cells, NEDD4 stabilizes the expression of KLF8 and promotes the transcriptional activity of KLF8 by promoting the ubiquitination of KLF8." (PMID 35031788, 2022). "NEDD4 and KLF8 were overexpressed in bladder cancer tissues and were associated with poorer patient survival rates." (PMID 35031788, 2022). "Our results suggest that NEDD4 augments the viability and invasive ability of bladder cancer by regulating the KLF8/miR-132/NRF2 axis." (PMID 35031788, 2022).
bladder cancer (continued). "The experimental data revealed that NEDD4 and KLF8 were overexpressed in bladder cancer tissues and cells and were associated with poor patient survival rates." (PMID 35031788, 2022). "In keeping with its proposed oncogenic function, NEDD4 has been shown to be overexpressed in several cancer types, including prostate and bladder cancer." (PMID 25823820, 2015). "NEDD4 regulates T cell-induced immune surveillance in bladder cancer." (PMID 38638430, 2024). "NEDD4 could be a key E3 ubiquitin ligase that regulates PD-L1 for destruction in FGFR3-driven bladder cancer." (PMID 38638430, 2024). "Therefore, NEDD4 targets PD-L1 for ubiquitination and destruction in FGFR3-overexpressing bladder cancer, indicating that NEDD4 is associated with immune surveillance via regulation of PD-L1 in bladder cancer." (PMID 37215134, 2023). "FGFR3 disrupts PD-L1 via NEDD4 to control T cell-mediated immune surveillance of bladder cancer." (PMID 37880682, 2023). "p-FGFR3 and NEDD4 co-localized at the cell surface of bladder cancer cells." (PMID 37497216, 2023). "FGFR3 destabilized PD-L1 via NEDD4 to govern T-cell-involved immune surveillance in bladder cancer." (PMID 36733484, 2023). "NEDD4 has been identified to take part in bladder cancer initiation and development." (PMID 37215134, 2023). "NEDD4 is highly expressed in bladder cancer and promotes tumor cell migration and invasion." (PMID 37497216, 2023). "Suppression of NEDD4 displayed antitumor activity in bladder cancer cells." (PMID 37215134, 2023). "Based on our results, we suggest that therapeutic strategies for bladder cancer should be directed toward the ablation of NEDD4, which may potentially be clinically viable targets for the prevention, detection and treatment of bladder cancer." (PMID 35031788, 2022). "Moreover, overexpression of NEDD4 enhanced cell proliferation, reduced cell apoptosis, and promoted cell invasion and migration in bladder cancer cells." (PMID 36293239, 2022). "The expression of NEDD4 and KLF8 in highly differentiated bladder cancer tissue (G1) was lower than that in moderately differentiated bladder cancer tissue (G2), while in poorly differentiated bladder cancer tissue (G3), NEDD4 and KLF8 exhibited the highest expression levels." (PMID 35031788, 2022). "Hence, in this study, we intended to characterize the functional relevance of the NEDD4-mediated Kruppel-like factor 8/microRNA-132/nuclear factor E2-related factor 2 (KLF8/miR-132/NRF2) axis in the development of bladder cancer." (PMID 35031788, 2022). "NEDD4 has a role in promoting the growth of hepatocellular and bladder cancer cell lines." (PMID 31856858, 2019). "Hence, natural compounds targeting NEDD4 could be useful to improve immunotherapy in bladder cancer." (PMID 37215134, 2023). "Combination treatment strategy for FGFR3 and NEDD4 could be useful for bladder cancer." (PMID 36733484, 2023). "Furthermore, we sought to examine whether NEDD4 regulates the viability and migratory ability of bladder cancer cells through KLF8." (PMID 35031788, 2022). "In bladder cancer, FGFR3 activation further intersects with IFN-γ signaling by modulating PD-L1 stability through NEDD4-dependent ubiquitination or by altering IFN-γ-induced PD-L1 turnover in FGFR3-TACC3 fusion models." (PMID 41514604, 2025). "In bladder cancer, FGFR3 can regulate PD-L1 ubiquitination and stability through phosphorylation of NEDD4, thereby affecting CD8+ T cell function." (PMID 41514604, 2025). "For example, NEDD4 overexpression leads to the suppression of PTEN expression and induces Notch-1, which leads to decreased apoptosis in RT4 bladder cancer (BCa) cells." (PMID 36293239, 2022). "Next, we cotransfected Flag-NEDD4, Myc-KLF8, and HA-Ub plasmids into T24 bladder cancer cells, and Myc was adopted for the IP assay to examine the ubiquitination of KLF8." (PMID 35031788, 2022).
bladder cancer (continued). "The 5-year overall survival analysis revealed that increased expression of NEDD4 and KLF8 was closely related to poorer survival rates of patients with bladder cancer." (PMID 35031788, 2022). "Our experimental data suggested that NEDD4 intensified the stability and transcriptional activity of KLF8 through ubiquitination to augment the viability and migratory ability of bladder cancer cells." (PMID 35031788, 2022). "The coexpression relationship between NEDD4 and KLF8 in bladder cancer was identified through the biological website Chipbase v2.0." (PMID 35031788, 2022). "Meanwhile, the correlation between the expression of NEDD4 and KLF8 in tumor tissues and clinicopathological parameters in bladder cancer was analyzed." (PMID 35031788, 2022). "In bladder cancer, PTEN levels were increased by NEDD4 silencing." (PMID 37497216, 2023). "This work provided a molecular clue among NEDD4, PD-L1 and FGFR3, suggesting that targeted therapy in combination with immune therapy could be much better for the treatment of bladder cancer." (PMID 37215134, 2023). "Moreover, we predicted the coexpression relationship between NEDD4 and KLF8 in bladder cancer via in silico analysis, which was validated in clinical samples." (PMID 35031788, 2022). "Therefore, this study aimed to delineate new mechanisms by which the NEDD4-mediated KLF8/miR-132/NRF2 axis exerts its oncogenic effects in the initiation and development of bladder cancer." (PMID 35031788, 2022). "In addition, the expression of NEDD4 and KLF8 was elevated in bladder cancer cell lines (EJ-m3, T24, J82, BIU-87, and SW780) compared to that of the normal urothelial cell line SVHUC-1, with the highest expression in T24 cells, which were therefore selected for subsequent experiments." (PMID 35031788, 2022).
pancreatic cancer (12 papers, 2014 to 2025). "In conclusion, we found that gemcitabine resistance in pancreatic cancer can be influenced by FTO that demethylates NEDD4 RNA in a m6A-dependent manner, which then influences the PTEN expression level and thereby affects the PI3K/AKT pathway." (PMID 37605223, 2023). "Further, in pancreatic cancer cells, NEDD4 prevents autophagy activity under metabolic stress by decreasing mitochondrial function and limiting tumor development by destabilizing an autophagy protein, ULK1, and a glutamine transporter, ASCT2." (PMID 36293239, 2022). "Another study revealed that NEDD4 lowered the Myc protein synthesis and decreased proliferation of neuroblastoma and pancreatic cancer cells by directly binding to Myc oncoproteins and targeting them for ubiquitination and degradation." (PMID 36293239, 2022). "NEDD4 was recently found to suppress the growth of neuroblastoma and pancreatic cancers by targeting Myc and RAS oncoproteins for ubiquitination and degradation." (PMID 31856858, 2019). "Taken together, our data shows that the NEDD4 mRNA is translationally activated in pancreatic cancer cells." (PMID 28423617, 2017). "Finally, we found that NEDD4 members showed increased expression in pancreas cancer and decreased expression in thyroid cancer." (PMID 37291499, 2023). "Similarly, downregulation of NEDD4 using curcumin in pancreatic cancer cell lines Patu8988 and Panc-1 resulted in a considerable reduction in tumor cell development, in association with increased expression of PTEN and p73." (PMID 36293239, 2022). "A study reported that NEDD4 targets Myc oncoproteins, c-Myc and N-Myc, for degradation by directly binding to them, which resulted in downregulation of these proteins and suppression of cell proliferation in pancreatic cancer and neuroblastoma." (PMID 36293239, 2022). "Furthermore, curcumin significantly inhibited wound closure and invasion of pancreatic cancer Patu8988 and Panc-1 cells, which was mediated by inhibiting neural precursor cell expressed developmentally down-regulated protein 4 (NEDD4)/Akt/mTOR pathway." (PMID 36009200, 2022). "Finally, we determined the mechanism behind differential NEDD4 protein expression in pancreatic cancer." (PMID 28423617, 2017). "Interestingly, FTO may attenuate gemcitabine resistance in Pancreatic cancer by modulating neural precursor cell expressed developmentally downregulated 4 (NEDD4) mRNA stability through the PTEN/PI3K/AKT signaling axis." (PMID 40986143, 2025). "Similarly, NDRG1 (N-myc downstream regulated gene-1) could also regulate NEDD4 expression in pancreatic cancer cells." (PMID 24657926, 2014). "FTO knockdown markedly increased the PTEN expression level by regulating NEDD4 expression and influenced the PI3K/AKT pathway, which led to chemoresistance to gemcitabine in pancreatic cancer cells." (PMID 37605223, 2023). "FTO knockdown markedly increased the PTEN expression level in an NEDD4-dependent manner and influenced the chemosensitivity to gemcitabine through the PI3K/AKT pathway in pancreatic cancer cells." (PMID 37605223, 2023). "In pancreatic cancer cells it has been shown that the metastasis suppressor, N-myc downstream regulated gene-1 (NDRG1) inhibits NEDD4 expression." (PMID 28423617, 2017). "Our findings indicate that NEDD4 potentially plays a critical role in activating the PI3K/AKT signaling pathway by negatively regulating PTEN levels in PDAC cells, which promotes pancreatic cancer cell proliferation and metastasis." (PMID 28423617, 2017). "In addition, FTO depletion significantly upregulates PTEN expression in a NEDD4-dependent manner, thereby regulating gemcitabine sensitivity via the PI3K/AKT pathway in pancreatic cancer cells." (PMID 40986143, 2025). "Finally, we demonstrated that AMPK1-360aa induces cellular autophagy via NEDD4/AMPK1 to promote the proliferation and invasion of pancreatic cancer cells." (PMID 39103892, 2024).
pancreatic cancer (continued). "Furthermore, similar observations were reported in pancreatic adenocarcinoma (PDAC) cell lines where NEDD4-regulated PTEN expression negatively and led to uncontrolled cell growth and metastasis of pancreatic cancer." (PMID 38097550, 2023).
keloid (11 papers, 2013 to 2025). An irregularly shaped, elevated mark on the skin caused by deposits of excessive amounts of collagen during wound healing. "The region around NEDD4 was previously found to contain an admixture mapping peak associated with keloid formation in African Americans, with the most significant result at MYO1E22." (PMID 40835838, 2025). "Increased expression of both PHLDA3 in not sun-exposed skin (p = 1.74 × 10-14, OR = 2.39 [1.91 – 2.99]) and NEDD4 in fibroblasts (p = 5.90 × 10-11, OR = 1.91 [1.57 – 2.31]) were associated with increased risk of keloids." (PMID 40835838, 2025). "In particular, we found that a LINE-1 insertion in an intron of NEDD4 is associated with keloids, which are abnormally protruding scars that form during the healing process of a skin injury." (PMID 38816353, 2024). "NEDD4 encodes a ubiquitin ligase involved in protein degradation and has been associated with susceptibility to keloids." (PMID 37033989, 2023). "In summary, we not only confirmed two susceptibility loci for keloid (1q41 and NEDD4 at 15q21.3) in the Chinese Han population but also indicated common genetic factors shared by both Chinese Han and Japanese populations." (PMID 23667473, 2013). "At 15p21.3, the SNP rs8032158 within NEDD4 was significant associated within keloid in populations of Japanese ancestry." (PMID 23667473, 2013). "Previously studies demonstrate that phosphatase and tensin homolog (PTEN), insulin-like growth factor I receptor (IGF-IR) and SMAD4 are substrates of NEDD4, which have been reported to be associated with keloid." (PMID 23667473, 2013). "NEDD4 is associated with chronic inflammatory diseases, and a single rs8032158 transcription variant (TV3) in the NEDD4 genome has been found in keloid patients to activate the NF-κB signaling pathway by binding to the connexin RIP and highly selectively expressed." (PMID 39185411, 2024). "A genome-wide association study with keloid patients in the Japanese population revealed an association between keloids and NEDD4, an E3 ubiquitin ligase acting as a positive autophagy regulator, thereby implicating the potential roles of autophagy in the pathogenesis of keloids." (PMID 36009363, 2022). "Notably, unique SNPs located within NEDD4 (chr15q21.2–22.3) independently showed association with keloid risk in multiple populations." (PMID 33202590, 2020). "In this study, we found rs2271289 located in the intron region of NEDD4 associated with keloid in the Chinese Han population (P = 1.02×10−11, OR = 0.66), rs8032158 had moderately LD with rs2271289 based on HapMap3 (CHB, D’ = 0.96, r2 = 0.41, and JPT, D’ = 1.0, r2 = 0.34)." (PMID 23667473, 2013). "NEDD4 promotes keloid progression by ubiquitinating and degrading PTEN, thereby hyperactivating the PI3K/AKT pathway." (PMID 41424791, 2025). "This review collects current knowledge on the molecular mechanisms underlying PI3K/AKT/mTOR activation in keloids and HTS, highlighting the roles of key regulators such as PTEN, NEDD4, and non-coding RNAs." (PMID 41424791, 2025). "The locus carrying the LINE-1 insertion colocalizes with the NEDD4 eQTL of fibroblasts, and by cellular experiments, LINE-1 was confirmed to function as an enhancer of a short NEDD4 transcript variant, which is involved in severe keloid formation." (PMID 38816353, 2024). "A multistage GWAS of keloid predisposition in a Japanese population identified several single nucleotide polymorphisms (SNPs; rs873549, rs1511412, rs940187, and rs8032158) in three chromosomal regions in linkage disequilibrium with SNPs in FOXL2 and NEDD4." (PMID 33202590, 2020). "The results suggested NEDD4 that might be a common genetic factor for the development of keloid within multiple populations in terms of Chinese Han and Japanese, although the most significant SNPs were different among them." (PMID 23667473, 2013).